MDM2 (MDM2 proto-oncogene)
Diseases named in the same sentence as MDM2 in open-access papers (continued):
Sharing a sentence is not in itself a finding about the gene and the disease.
tumor (continued). "Immunostaining of Mdm-2 varied considerably between the tumours." (PMID 16685270, 2006). "In all, 59 cases displayed nuclear staining, while in 41 of the tumours Mdm-2 could only be detected in the cytoplasm." (PMID 16685270, 2006). "Protein overexpression and gene amplification of Mdm2 are found in various types of tumours." (PMID 16641901, 2006). "Within this groupthe MDM2 gene was over-expressed in every tumour in which the gene amplification was found, and over-expression inthe absence of gene amplification was also found in an additional 10 tumours." (PMID 18521196, 1997). "However, 20q13 amplification occurred preferentially in stage 3 tumours and MDM2 was correlated to ERBB-2 amplification." (PMID 8980401, 1996). "Therefore, we screened 656 tumor samples for MDM2 amplification using FISH." (PMID 41299419, 2025). "Furthermore, in animal models, MA242 reduced MDM2 expression and effectively inhibited tumor growth dependent on MDM2 expression without causing host toxicity." (PMID 40046748, 2025).
tumor (continued). "Furthermore, we uncovered the underlying mechanism of 6PGD in promoting tumor growth and metastasis, which binds to ALKBH5 and inhibits the activity of ALKBH5, resulting in the increase of m6A modifications of MDM2 mRNA and the subsequent increase of its mRNA stability mediated by YTHDF2." (PMID 40611205, 2025). "Furthermore, combining the mdm2 inhibitor with a PD-1/PD-L1 blockage could lead to increased complete tumor regression rates." (PMID 41299419, 2025). "MDM2 amplification and the resultant MDM2 overexpression are hallmark features of both WDLPS and DDLPS, and cells within the tumors with these features may be interpreted as tumor-derived cells." (PMID 39125555, 2024). "Despite the diagnostic implications that the overlap of genetic alterations in neoplasms with changes in genes within the 12q13-15 region could create, the discovery of coamplifications of MDM2 with CDK4 and GLI1 offers new therapeutic targets in neoplasms with MDM2/CDK4 amplification." (PMID 38275873, 2024). "In addition, monotherapy with MDM2 antagonists is insufficient to suppress tumor progression." (PMID 38684550, 2024). "Furthermore, the expression of MDM2 is evident in multiple normal tissue types, potentially contributing to T lymphocyte central and/or peripheral tolerance, consequently impeding the effective control of tumor growth." (PMID 38281981, 2024). "However, tumor resistance poses a significant limitation to the efficacy of MDM2 inhibitors." (PMID 39263534, 2024). "The immunoexpression of IMP3 was observed in 21 of 92 (22.82 %) cases, CDK4 in 13 of 94 (13.82 %) cases, MDM2 in 17 of 99 (17.17 %) cases, and β-catenin in 8 of 90 (8.8 %) cases, with no significance for percentage of positive cells between the analyzed tumor's group." (PMID 39368400, 2024).
tumor (continued). "Nutlin-3(a) is an extensively researched small molecule inhibitor of MDM2 that has demonstrated antitumor effects by means of direct cytotoxicity and inhibition of proliferation while also modifying the tumor stroma and blood vessels in the tumor microenvironment." (PMID 38281981, 2024). "MDM2 may also promote tumor growth through other mechanisms." (PMID 39723387, 2024). "Hence, PUMA upregulation mediated by iodine-fortified lettuce could be the trigger for the epigenetic activation of tumor suppressor genes through the MDM2/RB/DNMT3A pathway." (PMID 37373017, 2023). "Besides, we found CDK4 and MDM2 amplifications with upregulated phospho-Rb in the recurrent tumor and its xenografts, suggesting the multiple deregulated cell cycle mechanisms to support tumor progression and facilitate xenograft formation in the present case." (PMID 38012788, 2023). "Interestingly, the value of MDM2 as a prognostic marker remains unclear and dependent on the tumour type." (PMID 37185737, 2023). "Microscopically, these tumors may consist of a range of different morphologies and the percentage of tumor cells with MDM2 amplification may vary in different areas of the tumor, which may affect the proper evaluation of FISH performed on a pre-surgical biopsy." (PMID 34986184, 2022).
tumor (continued). "However, a positive correlation between GATA2 and MDM2 expression in tumor tissues was observed." (PMID 34592889, 2021). "Importantly, this pathway can be targeted via MDM2 to activate tumour suppressive outcomes that may be able to bypass diverse mechanisms of resistance to CDK4/6i altogether." (PMID 34804982, 2021). "In addition, recent results indicate that MDM2 inhibitors may sensitise tumours to T-cell mediated killing in combination with anti-PD-1 therapy, regardless of changes in PD-L1 expression." (PMID 34911439, 2021). "A molecular testing panel of the tumor tissue showed the presence of 21 mutations (none of them treatable), including MDM2 (murine double minute 2), KRAS (Kirsten rat sarcoma) amplification, RB1 (retinoblastoma protein) amplification, and STK11 (serine/threonine kinase 11)." (PMID 34298855, 2021).
tumor (continued). "Thus, the balance between tumor suppressor induction and oncoprotein activation by MDM2-targeted drugs could tip the balance towards tumor regression or tumor survival, respectively." (PMID 32874188, 2020). "However, combination with DIM prevented the Nutlin-3a and RG-7388-induced increase of MDM2, which may explain the synergistic effects in tumor suppression." (PMID 32629830, 2020). "Hence, p14Arf exerts a double tumour suppressor activity via its interaction with MDM2." (PMID 32453417, 2020). "In addition, a positive correlation exists between NFAT1 and MDM2 in tumor tissues." (PMID 32397368, 2020). "The observation made by Seccherio and colleagues (2007) that MDM2 antagonist Nutlin-3 inhibits cell cycle progression and cell migration in HUVEC was one of the first lines of evidence that MDM2 could facilitate the activation of endothelial cells to support tumor angiogenesis." (PMID 31921839, 2019). "Consequently, the effect of MDM2 inhibitor on T cells could impact antitumor immune responses occurring in the context of MDM2 inhibitor-mediated tumor cell death." (PMID 31779710, 2019). "Similarly, recent studies demonstrated that MDM2 overexpression promotes angiogenesis process by inducing the balance of cytokine expression into an angiogenic status to achieve angiogenesis and enhance the migrative and invasive ability of tumor cells." (PMID 31440117, 2019). "From natural compounds up to small molecules and stapled peptides, these MDM2/X pharmacological inhibitors have been extensively studied, revealing different biological features and different rate of efficacy when tested in in vitro and in vivo experimental tumor models." (PMID 28673313, 2017). "However, the overall impact of MDM2 antagonists on the ability of MDM2 to ubiquitinate other target proteins requires further investigation since this could affect tumor cell response to the MDM2 antagonists." (PMID 29065514, 2017).